PLK1 (polo like kinase 1)
Diseases named in the same sentence as PLK1 in open-access papers (continued):
Sharing a sentence is not in itself a finding about the gene and the disease.
lung carcinoma (continued). "The manufacture of mesoporous silica in combination with anti-EGFR in the form of cetuximab was also carried out to deliver siRNA against polo-like kinase 1 (PLK1), which is critical in lung cancer mitosis." (PMID 36085575, 2022). "We screened mitotic kinase small molecule inhibitors against PLK1 (volasertib), Aurora kinase A (alisertib), and CHK1 inhibitor (AZD7762) in human and mouse lung cancer cell lines." (PMID 35871223, 2022). "Herein, we find that PLK1 knockdown also increases PD-L1 surface expression in both human (A549) and murine (LLC-JSP) lung cancer cell lines." (PMID 35871223, 2022). "It has been reported in previous literature that NEK2, TOP2A, PLK1, CA4, and AURKB can play oncogenic or tumor suppressing roles in the progression of lung cancer." (PMID 35646063, 2022). "When combined with BI-2536 (an inhibitor of polo-like kinase 1), Fasudil suppressed KRAS-mutant lung cancer growth in a corresponding LSL-KRAS (G12D) mouse model and in a patient tumor explant mouse model of KRAS-mutant lung cancer." (PMID 36230634, 2022). "To validate the antitumor immunity-activating effect of PLK1 inhibition in vivo, we used BI2536 to handle an established subcutaneous LLC mouse lung cancer model." (PMID 34522178, 2021). "In this study, the methylation profile of PLK1/2/3/4 was analysed in lung adenocarcinoma and lung squamous cell carcinoma, as well as prognostic value of PLK promoter methylation in lung cancer subtypes." (PMID 34080290, 2021). "Previously, we found that the levels of PLK1 and ABC transporters were highly upregulated in paclitaxel-resistant (TXR) lung cancer cells compared with those of parental cells." (PMID 34503223, 2021). "For a therapeutic approach to paclitaxel-resistant lung cancer, the EGFR inhibitor gefitinib and the PLK1 inhibitor volasertib or genistein were applied as a single reagent or combinatory reagents in parental and paclitaxel-resistant LUAD." (PMID 34503223, 2021). "To understand the expression of PLK1 and EGFR in chemoresistant lung cancer, we analyzed a published transcriptome of gemcitabine-resistant Calu3 lung adenocarcinoma cells (GSE 6914)." (PMID 34503223, 2021). "In this study, we performed an analysis of transcriptional and protein expression to identify overexpressed PLK1/4 and under‐expressed PLK2/3 in lung cancer subtypes." (PMID 34080290, 2021). "In summary, our in vitro and in vivo data demonstrate that FGFR1 and PLK1 inhibitors constitute a synergistic drug combination and that the FDA‐approved HCQ further enhances cytotoxicity of the treatment in KRAS‐mutant lung cancer." (PMID 34369083, 2021). "Based on this correlation between PLK1 and EGFR, the cumulative overall survival (OS) rates were analyzed in lung cancer patients." (PMID 34503223, 2021). "In contrast to PLK1 expression, PLK2/3 showed an under‐expression in lung cancer compared to normal sample." (PMID 34080290, 2021). "The expression of the lung cancer stem cell marker CD44 and TGF-β ligand TGFB1 was also reduced by the depletion of TNFAIP6 in active PLK1-expressing cells." (PMID 31548612, 2020). "In brief, we found that the USP7 was highly expressed concomitantly with the mitotic factors such as PLK1, CCNB1, CDC25A, and AURKB in prostate and lung cancer." (PMID 33207738, 2020). "Additional further investigation targeting PLK1 and USP7 would be interested in platinum-resistant lung cancer for clinical usage since platinum-based agents are also first in line for the treatment of NSCLC." (PMID 33207738, 2020). "CDCA genes probably exert their functions in tumorigenesis through the PLK1 pathway.CDCA gene family and patient survival data were examined for lung cancer (LC) patients from the GEPIA, Oncomine, cBioPortal, and Kaplan–Meier Plotter databases." (PMID 32104702, 2020).
lung carcinoma (continued). "Here, we show that snc886-3p is also associated with Argonaute in lung cell line WI-38, which is in agreement with the proposed microRNA identity of hsa-miR-886-3p (here snc886-3p) acting through direct repression of PLK1 and TGFB1 in lung cancer." (PMID 32093270, 2020). "Recently, dual targeting of PLK1 and WEE1 has been reported to elicit AZD1775’s single agent cytotoxicity in lung cancer." (PMID 29954437, 2018). "Activation of TBK1 at mitosis was previously reported and further shown to promote phosphorylation of Plk1 and metadherin in TBK1-sensitive lung cancer cells to maintain their survival." (PMID 25923723, 2015). "The library contained ~4,500 shRNAs targeting various signaling and cancer-related genes and was screened in four lung cancer cell lines using both high (IC80) and low (IC20) amounts of the PLK1 inhibitor GSK461364." (PMID 22248814, 2011). "Given the pivotal role of PLK1 and NRP1 in promoting lung cancer proliferation, dual inhibition of PLK1 and NRP1 may serve as a potential therapeutic strategy for lung cancer." (PMID 40820676, 2025). "In summary, through WGCNA and differential gene expression analysis, our study generated the significant genes, ASPM, CDCA8, CENP5, CEP55, and PLK1 that may be biomarkers and has potential for treatment in HIV‐infected lung cancer." (PMID 35608130, 2023). "In addition, we also found that PLK1, CDK1, CCNB1, and CCNB2 were upregulated in lung cancer, liver cancer, and cervix cancer tissues from HPA." (PMID 37007025, 2023). "Although both PLK1 and AHR are closely related to lung cancer tumorigenesis, whether they cooperate to accelerate tumor progression remains unknown." (PMID 37988371, 2023). "Taking all together, we hypothesized that the interaction of AHR and PLK1 was important in LUAD and thus focused on this lung cancer subtype for our study." (PMID 37988371, 2023). "Selective Polo-like kinase 1 Polo-Box Domain (PLK1 PBD) inhibitor MCC1019 (compound 2) is a bromomethyl-substituted benzofuran developed by Abdelfatah and colleagues for the treatment of lung cancer and evaluated via in silico, in vitro, and in vivo models." (PMID 35565325, 2022). "PLK1, EPHK10, and KIF4A also play important roles as prognostic indicators or as targeted therapy sites for the progression of multiple tumors, such as pancreatic cancer, esophageal squamous cell carcinoma, bladder cancer, and lung cancer." (PMID 35495629, 2022). "Other genes, including PLK1, CDCA8, ANLN, and RACGAP1, were all discovered to play different roles in proliferation, metastasis, and enhanced chemotherapy sensitivity to doxorubicin in lung cancer." (PMID 35464867, 2022). "Furthermore, the survival rates until first progression (FP) showed that the expression levels of PLK1 and EGFR mRNA and survival rates were correlated inversely in human lung cancer (n = 596, HR = 1.98, log rank P = 8.3 × 10−7)." (PMID 34503223, 2021). "As FGFR and PLK1 inhibitors are under active clinical development, our findings provide a new rationale of synergistic combination therapy that is readily translatable for patients with KRAS‐mutant lung cancer." (PMID 34369083, 2021). "In summary, we have provided insight into a novel signaling mechanism of TCTP regulation at the post-translational level in which the mTORC1/S6K signaling pathway negatively regulates a novel Akt/PLK1 axis and maintains TCTP at high levels in lung cancer cells." (PMID 34675258, 2021). "Accordingly, we observed that the transcriptional expression of DNMTs had a positive relation with PLK1/4 and a variously negative association with PLK2/3 in lung cancer subtypes." (PMID 34080290, 2021). "Thus, combined PLK1/FGFR1 inhibition abolishes ROS homeostasis, leading to oxidative stress‐activated JNK/p38/E2F1 signaling and induction of apoptosis in KRAS‐mutant lung cancer cells." (PMID 34369083, 2021).
lung carcinoma (continued). "Most PLK1 inhibitors involved in clinical trials have shown no response in different cohorts of lung cancer (both SCLC and NSCLC), so far." (PMID 32645997, 2020). "Furthermore, combination treatment with the mitotic kinase PLK1 inhibitor volasertib and the USP7 inhibitor P22077 showed a strong synergism through down-regulation of MDR1/ABCB1 in paclitaxel-resistant lung cancer." (PMID 33207738, 2020). "Therefore, we examined the relationships between BEX4 expression and PLK1 and CDK1 expression in human lung cancer cells." (PMID 30367032, 2018). "Immunoblotting analysis revealed that PLK1 was overexpressed in 10 of the 11 lung cancer cells, and unexpectedly, 9 of the lung cancer cell lines showed a significant positive correlation between the expression of BEX4 and the expression of PLK1 or CDK1." (PMID 30367032, 2018). "For example, in both lung cancer types, all the 24 HLA genes had negative expression correlations with the PLK1 expression in LUSC, and 19 HLA genes did in LUAD (Pearson correlation, FDR<0.1)." (PMID 30631355, 2018). "In search of TBK1 substrates responsible for survival in lung carcinoma, it was found that TBK1 phosphorylates the mitotic kinase PLK1, suggesting that TBK1 could regulate mitosis to drive lung cancer cell survival." (PMID 29971063, 2018). "Among them, five genes (ASPM, CDCA8, CENPF, CEP55, and PLK1) were present in both three hub gene lists (intersection gene, DEGs, and WCGNA module) suggesting that these five genes may become key genes involved in HIV‐infected lung cancer." (PMID 35608130, 2023). "Furthermore, we also found that PLK1, LDHA, FURIN, FSCN1, and RAB27B were increased in NSCLC cancerous cell lines compared with that in normal human bronchial epithelium cell line BEAS-2B, MS4A1 was down-regulated in lung cancer cells lines." (PMID 37604869, 2023). "By analyzing the expression profiles of EGFR and PLK1 in lung cancer patients using TCGA data from cBioPortal, we found that the expression levels of PLK1 and EGFR were correlated positively in lung cancer patients (Spearman factor 0.32, p = 1.65 × 10−9; Pearson factor 0.24, p = 1.159 × 10−5)." (PMID 34503223, 2021). "However, combination treatment with a USP7 inhibitor and PLK1 inhibitor exerts a strong synergistic effect in lung cancer cells resistant to paclitaxel, suggesting that co-targeting USP7 and PLK1 may be a valuable strategy for future clinical translation research." (PMID 33207738, 2020). "DNMT1/3A/3B were positively related with PLK1/4 in lung cancer subtypes, except the correlation between DNMT3A and PLK1 without significance in lung squamous cell carcinoma." (PMID 34080290, 2021). "We also observed a strong negative correlation between PLK1 and FGFR3 in EGFR‐mutant lung cancer cohort, whereas there are no such correlations in BRAF‐mutant lung cancer." (PMID 34369083, 2021). "Additionally, we also want to know if PLK1 OE in other cancer cell type leads to the decrease of PHGDH, so we overexpressed PLK1 in lung cancer cell line A549 and found the decrease of PHGDH and no change of PSAT1." (PMID 40475404, 2025). "Thus, paclitaxel-resistant lung cancers are more sensitive to gefitinib and readily undergo apoptotic cell death compared with non-resistant lung cancer, through downregulation of ABCB1, ABCC9, ABCG2, PLK1, and EGFR." (PMID 34503223, 2021). "PLK1 expression was higher in male than that in female patients, so was PLK4 expression between genders, whereas PLK2 presented no differential expression between male and female of lung cancer patients." (PMID 34080290, 2021).
colorectal cancer (69 papers, 2004 to 2026). A primary or metastatic malignant neoplasm that affects the colon or rectum. "Preclinical and clinical evidence supports PLK1 inhibition as a promising therapeutic strategy for KRAS-mutated colorectal cancer." (PMID 41362735, 2026). "Taken together, according to our microarray findings, BTF3 seems to be association with MAD2L2, MCM3, and PLK1 through regulatory effects in different stages of mitosis, which affect proliferation and cell cycle of colorectal cancer cells." (PMID 31263147, 2019). "Human polo-like kinase 1 (PLK1) expression has been associated with inferior outcomes in colorectal cancer." (PMID 26047016, 2015). "Additionally, high levels of PLK1 have been associated with improved survival rates in colorectal cancer patients with APC mutations." (PMID 40612941, 2025). "PLK1 inhibition using either siRNA or pharmacological inhibitors caused significant reductions in the invasiveness of glioblastoma, bladder carcinoma, renal cell carcinoma, anaplastic thyroid carcinoma, and colorectal cancer cells." (PMID 28953239, 2017). "This review summarizes the results of preclinical experiments and clinical trials of PLK1 inhibitors, with colorectal cancer as a focus, in hope of facilitating future investigations in this research field." (PMID 40852028, 2025). "Overexpression of PLK1 was observed in many types of cancer including colorectal cancer (CRC), and was often associated with poor prognosis of patients, indicating a role of PLK1 in tumorigenesis." (PMID 40852028, 2025). "Inactivation of this protein in senescent colorectal cancer cells led to the re-expression of cell cycle regulators such as polo-like kinase 1 (PLK1) and cell division cycle 25 (CDC25)." (PMID 39633108, 2025). "PLK1 is overexpressed in colorectal cancer and promotes the migration and invasion of colon cancer cells." (PMID 38355643, 2024). "AURKA, cyclin B1, and PLK1 proteins were highly upregulated in colorectal cancer SW480 and HCT‐116 cells compared with normal CCD841 cells." (PMID 38425293, 2024). "Tumors have been found to express PLK1 abnormally in numerous studies, including colorectal cancer, melanoma, cervical cancer." (PMID 39628476, 2024). "We found that PLK1 promotes colorectal cancer cell metastasis through the MEK/ERK signaling pathway." (PMID 39451218, 2024). "Recent research reported that aberrant upregulated PLK1 correlates with recurrence and poor prognosis in colorectal cancer patients." (PMID 36618405, 2022). "Plk1 was tested in therapies for primary colorectal cancer, prostate and pancreatic cancers, and rectal cancer." (PMID 36545330, 2022). "Knockdown of the expression of Plk1 by RNAi has been shown to inhibit the proliferation of pancreatic cancer and colorectal cancer cells." (PMID 36545330, 2022). "Previous studies have shown that Plk1 plays essential roles in therapies designed to treat a variety of cancers, including primary colorectal cancer, prostate and pancreatic cancers, and rectal cancer." (PMID 36545330, 2022). "For colorectal cancer, overexpression of PLK1 is indicative of a favorable prognosis with the same effect being revealed for colorectal tumors in a Plk1-inducible loss of function mouse model." (PMID 34065956, 2021).
colorectal cancer (continued). "Colorectal cancer data to evaluate PLK1 expression in paired tumor and normal tissue were generated by GSE39582 (CIT cohort), TCGA (COADREAD), GSE20842 (Gaedcke Rectum), and GSE6988 (Dong Colorectum)." (PMID 34881526, 2021). "Another study in colorectal cancer showed that Plk1‐mediated invasion occurs via phosphorylation of vimentin (Ser82), which in turn regulates the cell surface levels of β‐integrin, a key player in cell adhesion." (PMID 30859681, 2019). "Polo-like kinase 1 (PLK1) is a biomarker that can be used to evaluate the biological behavior and prognosis of the colorectal cancers and is considered as an oncogene by cell cycle progression." (PMID 31769427, 2019). "We have demonstrated that the Plk1 inhibitor TAK-960 is a potent anti-colorectal cancer therapy through in vitro cell line assays and patient-derived tumor xenograft models." (PMID 29402316, 2018). "Plk1 is upregulated in many tumor types including colorectal cancer (CRC) and portends a poor prognosis." (PMID 29402316, 2018). "Mutant KRAS-expressing HCT116 colorectal carcinoma cells have previously been used to investigate resistance to PLK1 inhibition by the ATP-competitive PLK1 inhibitor, BI2536." (PMID 28807782, 2017). "The current study engages these nanoparticles to deliver siRNA against PLK1 gene and exhibit significant knockdown in vivo, in a mouse xenograft model of colorectal cancer." (PMID 24159333, 2013). "Elevated PLK1 levels have been found in many adult cancers, including breast and colorectal cancer, and in pediatric cancers, including neuroblastoma and rhabdomyosarcoma." (PMID 22390279, 2012). "The human homologue PLK1 has been reported to be overexpressed in various tumors including non-small-cell lung cancer, melanoma, colorectal cancer, and non-Hodgkin lymphoma." (PMID 20126259, 2010). "Moreover, preclinical and clinical data suggest that PLK1 inhibition is effective in KRAS-mutant colorectal cancer, providing a rationale for more investigation on the combination efficacy with KRASG12C inhibition." (PMID 39807828, 2025). "Furthermore, PLK1 showed a synthetic lethal interaction with the KRAS function in colorectal cancer cells based on genome-wide RNAi screen." (PMID 41458961, 2025). "Our findings underscore the pivotal role of PLK1 in mediating chemoresistance and suggest that PLK1 inhibition may represent a potential therapeutic strategy for the management of aggressive colorectal cancer subtypes." (PMID 39451218, 2024). "Additionally, c-Jun, a component of AP-1, is also known as a transcriptional target of β-catenin in colorectal cancer 31 and is a possible transcriptional factor for PLK1 expression." (PMID 36793862, 2023). "Additionally, c-Jun, a component of AP-1 30, is known as a transcriptional target and binding partner of β-catenin in colorectal cancer 31 and is a possible transcriptional factor for PLK1 expression." (PMID 36793862, 2023). "However, Several PLK1 inhibitors targeting breast and colorectal cancers have entered clinical trials recently but have demonstrated weak antitumor capacity against solid tumors, and few studies have focused on the therapeutic role of PLK1 in LA." (PMID 37744268, 2023). "In colorectal cancer, PLK1 may promote the growth, invasion, and metastasis of colorectal cancer cells through the PDKI-PLK1-MYC signaling pathway." (PMID 34917126, 2021). "Indeed, siRNA against the PLK1 product using lipid nanoparticles (TKM-080301) has been tested (NCT01437007) for colorectal cancers with hepatic metastases by injecting into the hepatic artery." (PMID 31769427, 2019). "The current study was designed to evaluate the efficacy of the investigational Plk1 inhibitor TAK-960 in colorectal cancer (CRC) models as a single agent and to determine the anti-cancer effects of TAK-960 in combination with standard agents in patient-derived CRC xenografts." (PMID 29402316, 2018).